TFR2 (transferrin receptor 2)
Diseases named in the same sentence as TFR2 in open-access papers (continued):
Sharing a sentence is not in itself a finding about the gene and the disease.
hereditary hemochromatosis (32 papers, 2005 to 2026). An inherited metabolic disorder characterized by iron accumulation in the tissues. "Haemochromatosis Type 3 is classified as a very rare disease, with the pathogenic allele frequency of TFR2 hereditary haemochromatosis estimated at approximately 0.00008 to 0.0002." (PMID 39687529, 2024). "Based on clinical findings, laboratory results, cardiac MRI, and endomyocardial biopsy data, a diagnosis of haemochromatosis was confirmed, and mutations in the TFR2 gene, responsible for haemochromatosis Type 3, were identified." (PMID 39687529, 2024). "Other types of hereditary hemochromatosis are caused by mutations in the transferrin receptor-2 gene (TfR2), hemojuvelin gene (HJV), hepcidin gene (HAMP), and the ferroportin gene (SCL40A1)." (PMID 28270766, 2017). "Tfr2 alpha is the mainly transcribed isoform of the TFR2 gene, whose mutations are responsible of a form of hereditary hemochromatosis named HFE36." (PMID 27477597, 2016). "Mutations in HFE and transferrin receptor 2 (TFR2) cause hereditary hemochromatosis, which is characterized by an inappropriate hepcidin (HAMP) expression relative to body iron levels." (PMID 24155934, 2013). "TfR2 has a 30-fold lower affinity to iron-bound Tf, yet mutations to the TfR2 gene results in hereditary hemochromatosis." (PMID 23874300, 2013). "The Y245X Tfr2 mutant used here has been characterised previously and in humans the corresponding truncation mutation, Y250X, is associated with hereditary hemochromatosis (HH) type III." (PMID 24155934, 2013). "TfR2 mutations have been reported to underlie hereditary hemochromatosis indicating a pivotal role for TfR2 in the transcriptional regulation of hepcidin." (PMID 19924283, 2009). "In addition, the TFR2 is involved in hepatic iron overload and hereditary hemochromatosis, as shown in different TFR2-deficient mouse models including whole-body and liver-specific TFR2 knockout (KO) mouse and TFR2/HFE double KO mouse." (PMID 34199599, 2021). "Hereditary hemochromatosis (HH) type 3 is an autosomal recessive disorder of iron metabolism characterized by excessive iron deposition in the liver and caused by mutations in the transferrin receptor 2 (TFR2) gene." (PMID 26029709, 2015). "Essentially, HFE-related haemochromatosis (common type) and TFR2-related haemochromatosis (rare type) show late-onset, milder and gradual iron loading, and often involve liver and joint damage." (PMID 41882292, 2026). "Compared with hereditary hemochromatosis caused by HFE and TFR2, HAMP gene mutation has a greater risk of heart attack, skin changes, liver fibrosis, and hypogonadism." (PMID 39005658, 2024). "A wide range of global and tissue‐specific knockout mouse models, including Hfe‐, TfR2‐, Hjv‐ and Hamp1‐knockout mice, have been studied extensively in an effort to understand haemochromatosis and iron homeostasis in humans." (PMID 32108988, 2020). "The putative iron sensor, transferrin receptor 2 (TfR2), is expressed in the liver and mutations in this protein result in the iron-overload disease Type III hereditary hemochromatosis (HH)." (PMID 24639653, 2014). "Sensing of iron-transferrin concentrations apparently depends on transferrin receptor 2 (TfR2) and HFE, two molecules which are mutated in the adult form of hereditary hemochromatosis." (PMID 20066043, 2010). "In addition to the essential role of Hfe and TfR2 in hepatic Hepc regulation, abnormal iron metabolism in myeloid cells/macrophages has been documented in patients with hereditary hemochromatosis." (PMID 39273097, 2024). "Genetic variants leading to excess body iron occur mainly in the haemochromatosis (HFE) gene but are also seen in hepcidin (hepcidin antimicrobial peptide (Hamp)), transferrin receptor 2 (TFR2), solute carrier family 40 member 1 (SLC40A1), haemojuvelin (HJV) and transferrin (TF) genes." (PMID 32609760, 2020).
hereditary hemochromatosis (continued). "Mutations of transferrin receptor-2 gene (TfR2), hemojuvelin gene (HJV), hepcidin gene (HAMP) and the ferroportin gene (SCL40A1) contribute to less frequent forms of hereditary hemochromatosis." (PMID 30340370, 2018). "In addition to the TFR2 gene, mutations of the HAMP and FPN1 genes also cause hereditary hemochromatosis." (PMID 26527688, 2015). "However, due to clinic resource limitations, the patient was only tested for HFE gene mutations, not any TFR2 or ferroportin mutations that less commonly cause hereditary hemochromatosis." (PMID 39723309, 2024). "Hepcidin levels are more markedly decreased in HJV-related haemochromatosis compared to HFE and TFR2 types." (PMID 41882292, 2026). "A liver biopsy showed an almost normal liver specimen with a slight deposition of iron in 2-3% of hepatocytes, and a genetic examination of hereditary hemochromatosis revealed no typical mutations in HFE, TFR2, HJV, HAMP, or SLC40A1." (PMID 36968338, 2023). "Other types of hereditary hemochromatosis are rare and broadly defined as non-HFE hereditary hemochromatosis and include mutations in the hemojuvelin gene, hepcidin (HAMP gene), transferrin receptor 2 gene, and ferroportin gene." (PMID 32641120, 2020). "Mutations of the TFR2 gene cause iron overload disease, hereditary hemochromatosis, and the affinity of TFR2 to holo-TF was 25-fold lower when compared with that of TFR1, indicating that TFR2 functions as an iron sensor unlike TFR1 (7, –, 9)." (PMID 26527688, 2015). "Non-HFE hereditary hemochromatosis is mostly associated with pathological mutations of proteins, which orchestrate iron homeostasis, such as hepcidin (HAMP), ferroportin (FPN), hemojuvelin (HJV) and transferrin receptor 2 (TFR2)." (PMID 35453939, 2022). "Sensing of acute changes in serum iron concentration and transferrin saturation also converges on the BMP–SMAD pathway, involving transferrin receptor 1 (TfR1/CD71), transferrin receptor 2 (TfR2), the haemochromatosis protein HFE and BMP receptors (although not requiring BMP6 induction)." (PMID 30995720, 2019).
iron deficiency (21 papers, 2009 to 2026). "The regulatory mechanism at the basis of the preferential skewing towards the production of platelets instead of RBC in iron deficiency remains to be fully explained, although a role for the TFR2/ERK pathway has been proposed." (PMID 40012014, 2025). "Overall, our study reveals that Hfe and TfR2 in macrophages regulate hepatic Hepc production and affect iron homeostasis in the spleen and BMDMs, leading to an iron deficiency in aged animals that impairs their erythropoiesis." (PMID 39273097, 2024). "Whereas mice deficient in TFR1 die in utero with severe iron deficiency, Tfr2-mutated mice display iron overload due to increased iron absorption from the intestine." (PMID 34360974, 2021). "On the other hand, iron deficiency partially attenuated the induction of splenic TFR2 protein by EPO, suggesting that both liver and splenic TFR2 proteins are to some extent posttranscriptionally regulated by iron availability." (PMID 30958854, 2019). "In the liver, TFR2 expression is posttranscriptionally regulated by diferric transferrin; in erythroid cells in vitro, TFR2 is cleaved from the cell surface in iron deficiency." (PMID 29073189, 2017). "By using immunohistochemistry, the expression of TfR1 and TfR2 is significantly higher in human HCC tissues than in adjacent non-tumor tissues, suggesting that TfR1 and TfR2 are expressed in response to iron deficiency during liver carcinogenesis." (PMID 25476483, 2015). "Tmprss6-/-Tfr2-/- double knock out animals develop iron deficiency with high hepcidin, a phenotype similar to Tmprss6-/- mice and to Tmprss6-/-Hfe-/- animals." (PMID 24847265, 2014). "Tfr2 function becomes more evident in iron deficiency, as exemplified by Tmprss6-/-Tfr2-/- double knock out mice." (PMID 24847265, 2014). "Further studies are needed to clarify the molecular mechanisms that mediate the TFR2 function in iron deficiency." (PMID 24847265, 2014). "Fetal liver TfR expression was unchanged by maternal iron deficiency throughout pregnancy, while TfR2 expression was decreased." (PMID 23110188, 2012). "Surface expression of TfR2 is downregulated in iron deficiency." (PMID 35634155, 2022). "TFR2 in the bone marrow might be a sensor of iron deficiency that protects against excessive microcytosis in a way that involves EPOR, although the mechanisms remain to be worked out." (PMID 24847265, 2014). "In iron deficiency, the regulation pathway for iron status includes activity of the BMP/HJV and HFE/TFR2 complex." (PMID 24894955, 2014). "Iron deficiency enhances erythropoiesis by increasing renal erythropoietin (EPO) production and erythroblastic EPO sensitivity via the genetic loss of the EPO receptor (EPOR) partner transferrin receptor 2 (TfR2)." (PMID 37108056, 2023). "Tfr1 mRNA has five iron-responsive elements in its 3-untranslated region, which mediate the induction of TFR1 during states of iron deficiency; no such sequences are present in Tfr2 mRNA." (PMID 34360974, 2021). "We also show that the synthesis of ERFE protein in the spleen of EPO-treated mice is not affected by iron pretreatment, and that iron deficiency posttranscriptionally downregulates TFR2 protein content in the spleen of erythropoietin-treated mice." (PMID 30958854, 2019). "Although splenic TFR2 protein content was not influenced by iron overload, iron deficiency partially attenuated the EPO-induced increase in splenic TFR2 protein." (PMID 30958854, 2019). "Taken together, lower expression of proteins that deliver iron to the cells and the lack of differences in FPN and TfR-2 proteins expression may be one of the mechanisms of iron deficiency in heart failure." (PMID 35160288, 2022). "However, the expression of brain hepcidin is altered in TfR2-deficient mice in response to systemic iron deficiency or iron overload, suggesting that TfR2 is not the sole regulator of brain hepcidin expression." (PMID 35014607, 2022). "EPO-induced splenic Tfr2 mRNA content was not influenced by iron deficiency." (PMID 30958854, 2019).
iron deficiency (continued). "A prevalent role of erythroid TFR2 in iron deficiency might explain why this role is not evident in mice nor in patients with type 3 hemochromatosis, who are iron loaded and never experience iron deficiency." (PMID 24847265, 2014). "While TfR1 is moderately inducible by hypoxia and iron deficiency via HIF and iron regulatory proteins (IRPs), TfR2 expression is not known to be regulated by these stimuli." (PMID 19924283, 2009).
anemia (8 papers, 2011 to 2025). A reduction in the number of red blood cells, the amount of hemoglobin, and/or the volume of packed red blood cells. "Moreover, the inhibition of both TMPRSS6 and TfR2 gave interesting results in Hbbth3/+ thalassemic mice: even with the iron overload due to the TfR2 double mutation, a therapeutic effect on both erythropoiesis and anemia was obtained." (PMID 36079046, 2022). "Anemia robustly increased expression of transferrin-a (tfa), solute carrier family 40 member 1 (slc40a1 or fpn1), and transferrin receptor 2 (tfr2), reflecting activation of an iron-mobilization response to meet erythropoietic demand (p < 0.05)." (PMID 41471763, 2025). "The inactivation of the EPO receptor partner, TfR2, in a knockout thalassemia intermedia mouse model improved erythropoiesis and red blood cell morphology, as well as anemia and iron overload." (PMID 36079046, 2022). "Significant up-regulations were observed for the iron transporter tf, as well as its receptors, tfr1 and tfr2, and also of the iron exporter fpn, for both anemia levels." (PMID 27100629, 2016). "In IRIDA and anemia of chronic disease (ACD), where abnormally high Hepc causes the onset of an iron deficiency condition, Tfr2 downmodulation might be beneficial to decrease Hepc hyperproduction." (PMID 30360575, 2018). "Interestingly, this knock-in mouse model (Tfr2 KI), specifically lacking the Tfr2β-isoform (α+β0), is characterized by normal transferrin saturation, liver iron concentration, Hepc, and Bmp6 levels, but shows transient anemia at a young age." (PMID 30360575, 2018). "EPO treatment increased TFR2 protein both in C57BL/6 and mask mice, suggesting that the failure of EPO to correct the microcytic anemia in mask mice is not related to defective synthesis of this protein." (PMID 29073189, 2017).
hepatoma (8 papers, 2009 to 2025). "In hepatoma cell lines TFR2 is stabilized on cell surface by the addition of holo-transferrin to the culture media, an effect due to the increased protein half-life." (PMID 24847265, 2014). "Intriguingly TfR2 mRNA, which was less abundant than TfR1 mRNA in both hepatoma cell lines, was moderately increased by hypoxia, and reduced by DMOG and DP in Huh7 cells (upper panel and bar graph)." (PMID 19924283, 2009). "To test if CB1 receptor signal could lead to the induction of ERRγ and TFR2 protein, we performed Western blot analysis in Huh7, another human hepatoma cell line, and AML12 cells treated with ACEA." (PMID 34199599, 2021). "This has been observed in hepatoma derived and in erythroid cells, supporting the hypothesis that TFR2 may function as a signaling receptor." (PMID 24847265, 2014). "However, HNF4α knockdown greatly suppressed TFR2 expression in human hepatoma cells, indicating that there might be additional HNF4α-binding sites within the proximal promoter." (PMID 26527688, 2015). "Using primary hepatocytes from mice and a hepatoma cell line, it was shown that BMP2, 4 and 9 can induce hepcidin transcription independently of Hfe, Tfr2 or Il6 (interleukin 6)." (PMID 26182354, 2015). "Although the differences between TfR1 and TfR2 are not fully understood, it has been reported that the TfR-mediated transferrin-bound iron uptake is mediated primarily via TfR1 but not TfR2 in HuH7 human hepatoma cells." (PMID 33334049, 2020). "TFR2 is present in high levels in hepatocellular carcinoma, but there is little evidence for its presence in most cancers." (PMID 27898674, 2016).
juvenile hemochromatosis (6 papers, 2011 to 2021). "Type 2 HH, known as juvenile hemochromatosis, is caused by variants of the hepcidin (HAMP) and hemojuvelin (HJV) genes, while type 3 HH is related to variants of the TfR2 (TFR2) gene." (PMID 34067164, 2021). "In agreement with this, subjects with mutations in both TFR2 and HFE present with a more severe form of disease compared to patients with either TFR2 or HFE mutations alone, with a phenotype similar to juvenile hemochromatosis." (PMID 24155934, 2013). "Although non-HFE related HH due to mutations on the HFE2 gene is classically known as juvenile hemochromatosis, cases of non-HFE related HH with mutations in TFR2 gene are also young patients (A.II.1 35 years old, A.II.2 37 years old, B.II.1 46 years old and C.II.2 25 years old)." (PMID 34946929, 2021).
type 3 hemochromatosis (6 papers, 2014 to 2024). "Type 3 hemochromatosis is associated with mutations in the TFR2 (Transferrin Receptor 2) gene and has an intermediate onset, typically in young adulthood." (PMID 39323676, 2024). "Mutations of TFR2 in human and germline or hepatocyte-specific deletion of Tfr2 in mice cause type 3 hemochromatosis." (PMID 35758636, 2022). "Mutations in the transferrin receptor 2 (TFR2) gene were identified as a cause of hemochromatosis type 3 (MIM #604250)." (PMID 27363994, 2016). "Deleting Tmprss6 in the two hemochromatosis type 3 models, Tfr2-/- and Tfr2LCKO mice, revealed similarities but also differences in the hematological phenotype of the resulting double knock-out animals." (PMID 24847265, 2014).
glioblastoma (5 papers, 2018 to 2023). The most malignant astrocytic tumor (WHO grade IV). "An elevated TFR2 expression was identified in the colon, glioblastoma (GBM), and ovarian cancer cell lines." (PMID 37361050, 2023). "In contrast, although TFR2 is also significantly up-regulated in glioblastoma, but its up-regulation predicts a good prognosis for glioblastoma." (PMID 34858857, 2021). "Studies in glioblastoma and leukemia have established a correlation between TfR2 expression and tumor grade, but TfR2 overexpression also increased sensitivity to chemotherapy and, thus, is associated to favorable prognosis." (PMID 33287315, 2020). "Transferrin receptor 2 (TfR2) is frequently and highly expressed in glioblastoma (GBM)." (PMID 36072803, 2022). "Moreover, in glioblastoma TB10 cell line under hypoxic condition, a marked increase of TFR2 transcription was observed." (PMID 30360575, 2018).
myelodysplastic syndrome (5 papers, 2017 to 2023). A clonal hematopoietic disorder characterized by dysplasia and ineffective hematopoiesis in one or more of the hematopoietic cell lines. "Furthermore, low expression of both TFR2 transcripts was associated with poorer survival rates in patients with myelodysplastic syndrome with excess blasts than for those with normal to high TFR2 levels." (PMID 29771984, 2018). "Also, the presence of macrocytosis together with a low reticulocytes number and increased BM apoptosis in Tfr2 KO mice resembles the erythropoiesis of myelodysplastic syndromes (MDS)." (PMID 28540293, 2017). "High expression of TFR2 in erythroid cells and its role in erythroid differentiation have led to speculation of a clinically relevant role in haematological disorders such as myelodysplastic syndrome (MDS) and acute myeloid leukaemia (AML)." (PMID 29771984, 2018). "However, in subjects with myelodysplastic syndrome, acute myeloid leukemia, and GBM, the higher transcription levels of TFR2 were connected to a better prognosis than that in the lower group." (PMID 37361050, 2023). "*p<0.05 vs. WT; **p<0.01 vs. WT; Abbreviations: WT = wild type; MDS = myelodysplastic syndrome; DFP = deferiprone; TFR2 = transferrin receptor 2; ProE = pro-erythroblasts; BasoE = basophilic erythroblasts; PolyE = polychromatophilic erythroblasts; OrthoE = orthochromatophilic erythroblasts." (PMID 38153418, 2023).
ovarian carcinoma (3 papers, 2023 to 2024). A malignant neoplasm originating from the surface ovarian epithelium. "To investigate the expression patterns of these transferrin receptors in ovarian cancer, we conducted a study analyzing the protein expression of TFR1 and TFR2 in ovarian cancer tissues." (PMID 38740757, 2024). "Conversely, 8 genes showed increased expression in ovarian cancer tissues, including LCN2, CP, TFR2, LRP2, MELTF, LTF, SLC11A2, and STEAP3." (PMID 38186569, 2023).